ATRX (ATRX chromatin remodeler)
Diseases named in the same sentence as ATRX in open-access papers (continued):
Sharing a sentence is not in itself a finding about the gene and the disease.
neuroblastoma (continued). "Sporadic α-thalassaemia/mental retardation syndrome X-linked (ATRX) mutations have been detected in a subset of neuroblastoma patients mainly in children older than 18 months having poor prognosis." (PMID 30760980, 2019). "TERT mutations were found on whole genome sequencing in high risk neuroblastoma, although these only occurred in the absences of ATRX mutations or MYCN amplification." (PMID 30154341, 2018). "ATRX was found to be mutated in approximately 50% of adolescent and young adults with neuroblastoma." (PMID 28055978, 2017). "Putative genetic loss-of-function alterations in the ATRX gene have been identified in nearly 10% of neuroblastomas, and enriched in older patients." (PMID 28055978, 2017). "Although loss of function mutations or deletions of ATRX have been implicated in the pathogenesis of neuroblastoma, we found only 3 putative loss of function mutations in this study." (PMID 29296183, 2017). "ATRX, a gene plays an important role in epigenetic regulation, was found to be mutated in approximately 50% of adolescent and young adults with neuroblastoma." (PMID 28055978, 2017). "Although the mechanism is poorly understood, neuroblastoma tumors with ATRX loss of function mutations were found to have lengthened telomeres." (PMID 28055978, 2017). "Additional five mutated genes (LRRC17, PXDN, FZD1, ARHGEF10L, ATRX) were highly expressed in neuroblastoma and involved in cancer progression." (PMID 27009842, 2016). "Other genes (PTK2, NAV3, NAV1, FZD1 and ATRX), expressed in neuroblastoma and involved in cell invasion and migration were mutated at frequency ranged from 4% to 2%." (PMID 27009842, 2016). "With a clinically relevant example on detecting rare somatic CNVs within ATRX associated with neuroblastoma, CODEX is shown to be applicable to a wide range of study designs for CNV detection using WES data." (PMID 25618849, 2015). "Whole genome sequencing of the index liver metastasis identified 44 non-synonymous somatic mutations in 42 genes (0.85 mutation/MB) and a large hemizygous deletion in the ATRX gene which has been recently reported in neuroblastoma." (PMID 24147068, 2013). "Loss-of-function somatic ATRX mutations including large deletions was recently reported in neuroblastoma by three independent studies." (PMID 24147068, 2013). "As the understanding of how ATRX influences aggressivity in MYCN non-amplified neuroblastoma is similar to that found in MYCN amplified neuroblastoma, an important aspect of this will be to explore therapeutic vulnerabilities in patients with ATRX mutation and ATRX loss protein." (PMID 40286729, 2025). "•ATRX mutations in neuroblastoma tend to have a progressive course of disease." (PMID 40286729, 2025). "However, evidence is mounting that there are also significant differences between ATRX IFF and ATRX LoF neuroblastoma in the underlying mechanisms of epigenetic deregulation." (PMID 41380652, 2025). "Interestingly, GSEA of patient samples revealed upregulation of inflammatory response-related pathways in ATRX-mutated neuroblastomas, in line with our results." (PMID 39892705, 2025). "Altogether our results strongly indicate that multiple types of mutation impacting ATRX function may associate with an inflammatory phenotype and infiltration of macrophages in neuroblastoma models." (PMID 39892705, 2025). "A limited number of genetic alterations have been identified as drivers of neuroblastoma, including somatic ATRX gene alterations which are identified in 10 % of high-risk neuroblastomas and define a distinct sub-group of patients with chronic, slowly progressive disease." (PMID 41380652, 2025).
neuroblastoma (continued). "However, ATRX mutations in neuroblastomas are often in-frame deletions that remove approximately half of the amino terminus of the protein." (PMID 40286729, 2025). "However, it is currently unclear if ATRX mutations and/or the immunogenic phenotype are associated with sensitivity to immunotherapies commonly used in children with neuroblastoma including anti-GD2 antibody, which is currently given as standard of care." (PMID 39892705, 2025). "ATRX mutations are found in 55 % of ALT-positive neuroblastomas." (PMID 39892705, 2025). "ATRX is one of the most frequently mutated genes in high-risk neuroblastoma." (PMID 39892705, 2025). "•ATRX mutations are associated with age at diagnosis in patients with neuroblastoma." (PMID 40286729, 2025). "ALT inhibition could also be considered in the clinical trials for those patients with neuroblastoma having loss of ATRX." (PMID 35053227, 2022). "Furthermore, it has been described that inactivating ATRX mutations are mutually exclusive with MYCN amplification in neuroblastoma." (PMID 35406561, 2022). "Furthermore, the increased sensitivity of ATRX-deficient cells to RTKi (i.e., sunitinib) has been recently shown in other cancer cell types, such as neuroblastoma, reinforcing our findings." (PMID 35406561, 2022). "The discovery of rearrangements inducing the overexpression of TERT in the absence of MYCN-amplification or the mechanisms of the alternative lengthening of telomeres (ALT), often due to mutation or deletion of ATRX, identified telomere maintenance as a feature defining high-risk neuroblastomas." (PMID 34442335, 2021). "TERT rearrangements and ATRX mutations are also commonly observed in neuroblastoma." (PMID 34458583, 2021). "We previously reported age-associated ATRX alterations in a cohort of 104 neuroblastoma patients." (PMID 33056981, 2020). "Approximately half of ALT neuroblastomas are associated with somatic alterations in ATRX." (PMID 32375866, 2020). "Significantly higher ATRX-mutation frequencies are detected in patients with International Neuroblastoma Staging System (INSS) stage 4 disease (8.6%), high-risk subgroup (14.6%), 11q loss of heterozygosity (LOH), or unfavorable histology and in those who are 18 mo or older at diagnosis." (PMID 32060267, 2020). "To determine whether an elevated level of MYCN is incompatible with ATRX mutation in human neuroblastoma cells in vivo, we performed an in vivo growth competition assay." (PMID 32060267, 2020). "Nevertheless, these findings suggest that anti-telomerase-based therapies might benefit neuroblastoma patients with ATRX mutations." (PMID 28055978, 2017). "Additionally, the ATRX gene, a putative driver gene in the oncogenesis of Neuroblastoma, shows a gene deletion, but few mutations." (PMID 28056863, 2017). "Also, other mutations like PHOX2B and ATRX as well as epigenetic aberrations have been reported in neuroblastoma." (PMID 27036398, 2016). "The presence of the deletion in the diagnostic tumor sample Met1 and the primary tumor (PT) suggested the importance of this event for tumorigenesis, and this result was also consistent with the finding of frequent ATRX mutations in adolescent and young adult patients with neuroblastoma." (PMID 24147068, 2013). "Next, we asked whether ATRX IFF mutations also mediate an inflammatory phenotype in neuroblastoma." (PMID 39892705, 2025). "Given our findings and the increasing role of immunotherapy in the management of high-risk neuroblastoma, it is imperative that ongoing and future clinical trials of both standard of care and novel immunotherapy agents evaluate whether ATRX status is a biomarker of clinical response to these agents." (PMID 39892705, 2025). "However, because ATRX loss is due to structural alterations in the ATRX gene, including in-frame deletions, missense, nonsense and frame-shift single-nucleotide variations (SNVs), it would be difficult to regain the expression of ATRX in neuroblastoma." (PMID 35053227, 2022).
neuroblastoma (continued). "MYCN is a known transcriptional activator of TERT, yet MYCN amplifications were mutually exclusive with TERT rearrangements, as well as ATRX alterations, a gene associated with alternate lengthening of telomeres, suggesting that these alterations may share a similar role in neuroblastoma." (PMID 28587062, 2017). "Here, we show impairment of the response to differentiation stimuli in both stem cell and neuroblastoma models with ATRX LoF." (PMID 41380652, 2025). "Taken together this work shows that the mechanism of differentiation block in neuroblastoma depends on the type of ATRX alteration, with implications relating to both oncogenesis and therapeutic response." (PMID 41380652, 2025). "Taken together this shows that the mechanism of differentiation in ATRX-altered neuroblastoma depends on the type of ATRX alteration, with implications relating to both oncogenesis and therapeutic response." (PMID 41380652, 2025). "Given that RA is also used clinically as a differentiation therapy for patients with neuroblastoma, we next asked if a similar phenotype was seen when ATRX LoF neuroblastoma cells were treated with RA." (PMID 41380652, 2025). "We identified widespread differences in chromatin accessibility in ATRX LoF compared with ATRX WT neuroblastoma in both vehicle control conditions and upon treatment with RA." (PMID 41380652, 2025). "The most frequent type of ATRX alterations seen in neuroblastoma are in-frame multi-exon deletions, most commonly resulting in the loss of exons 2-10 of the gene (containing the EZH2 and ADD domains), and resulting in an in-frame fusion (IFF) protein." (PMID 41380652, 2025). "In neuroblastoma, there is a strong association between ALT and loss of function (LoF) gene variants in ATRX." (PMID 40115016, 2025). "Here, we identify that ATRX IFF neuroblastoma is also generally sensitive to RA, and that ATRX IFF cell lines mount an appropriate epigenetic response to RA." (PMID 41380652, 2025). "We treated paired ATRX wild-type and LoF neuroblastoma cell-lines with RA: cells with ATRX LoF fail to upregulate direct RA target genes and show reduced chromatin accessibility differentiation and development related genes following RA treatment." (PMID 41380652, 2025). "As in patients with ATRX IFF neuroblastoma, each model used in this study has a different genetic background and differences in precise co-ordinates of the in-frame deletion, which will likely also affect therapeutic sensitivities." (PMID 41380652, 2025). "Our data suggests a high likelihood of RA resistance in ATRX LoF neuroblastoma, although the limitation of our study is that we were unable to directly evaluate sensitivity due to a lack of relevant models." (PMID 41380652, 2025). "The key GO terms with an increase in accessibility in ATRX LoF cells were in acute inflammatory response pathways, consistent with our work identifying an immunogenic phenotype in ATRX-altered neuroblastoma." (PMID 41380652, 2025). "Here, our novel insight into the effects of ATRX LoF on neuroblastoma cell differentiation was triggered by an initial observation made in ATRX LoF iPSCs." (PMID 41380652, 2025). "In conclusion, our findings add to the increasing evidence that ATRX mutant neuroblastoma represents a biologically distinct subgroup of patients." (PMID 39892705, 2025). "Concordant with our findings in ATRX LoF iPSCs, we also identified a failure of upregulation of direct RA target genes in neuroblastoma cells with ATRX LoF." (PMID 41380652, 2025). "Taken together, this highlights the differences in response to current treatment protocols between subgroups and identifies the urgent need to find alternative approaches to treat patients with ATRX mutant neuroblastoma." (PMID 39892705, 2025). "Conversely, ATRX IFF neuroblastoma models are broadly sensitive to RA and show appropriate opening of chromatin at RA response sites." (PMID 41380652, 2025).
neuroblastoma (continued). "Due to a lack of experimental models and limited understanding of ATRX biology, there is a scarcity of novel targeted therapies for children with ATRX-mutant neuroblastoma." (PMID 39892705, 2025). "Both ATRX IFF neuroblastoma cell lines showed sensitivity to RA as a single agent and their clonogenicity was further reduced with the addition of either tazemetostat or the EZH2 degrader MS1943, at doses sufficient to reduce H3K27me3 levels." (PMID 41380652, 2025). "We also confirmed previous reports that the CHLA-90 and SK-N-MM models of ATRX IFF neuroblastoma were sensitive to the EZH2 inhibitor tazemetostat." (PMID 41380652, 2025). "Consistent with the in vivo models and patient datasets, a significant increase in CD68 positive macrophages was identified in ATRX mutant neuroblastomas compared with MYCN-amplified or non MYCN-amplified disease." (PMID 39892705, 2025). "Mutations in the chromatin remodeler ATRX and its partner DAXX are strongly associated with ALT while MYCN amplification is observed in telomerase-dependent/ALT-negative neuroblastomas." (PMID 38837897, 2024). "So far 30 unique ATRX MEDs have been reported in neuroblastoma, of which only three constitute the far majority of cases." (PMID 37540673, 2023). "Although mutations in ATRX and the TERT promoter are mutually exclusive, the coexistence of ALT and telomerase activity has been observed in some tumors, including neuroblastoma, sarcoma, breast cancers and pHGG." (PMID 37370681, 2023). "Previous studies have demonstrated potential connections between ATRX/DAXX, H3-3A (encoding for H3.3 histone variant) mutations and ALT use, especially in oligodendrogliomas, medulloblastomas, neuroblastomas and GBM." (PMID 37370681, 2023). "To study the role of ATRX aberrations in neuroblastoma development, we acquired two classical neuroblastoma cell lines, SK-N-MM and CHLA-90, and the tumoroid AMC772T2 that we had previously established in our lab." (PMID 37540673, 2023). "In this study we identified a dichotomy in ribosome biogenesis and several related metabolic processes between the ATRXΔ2–10 and the ATRXΔ2–13&-/- (ATRXΔ2–13 and ATRX-/-) neuroblastoma tumor cells." (PMID 37540673, 2023). "Altogether, two distinct expression profiles are present within ATRX aberrant neuroblastoma that seem to lead to opposing changes in metabolic processes." (PMID 37540673, 2023). "The reduction of ATRX level in ALT ATRX wild-type neuroblastoma can be accomplished by lowering DAXX level." (PMID 36860927, 2023). "Utilizing these models, we identified two opposing expression patterns within ATRX aberrant neuroblastoma and a potential role of ATRX in ribosome biogenesis." (PMID 37540673, 2023). "To study the molecular landscape of ATRX aberrant neuroblastoma we assessed the transcriptomes by performing total RNA-sequencing." (PMID 37540673, 2023). "In order to study the molecular role of different ATRX aberrations in neuroblastoma, we created isogenic ATRX knock-out (KO) and several distinct in-frame MEDs, including some rare deletions, in neuroblastoma cell line and tumoroid models." (PMID 37540673, 2023). "Previously, we have shown that ATRX multi-exon deletions (MEDs) are almost exclusively present in neuroblastoma whereas other pediatric cancers are dominated by point mutations." (PMID 37540673, 2023). "Additional study found that ATRX alterations, such as in-frame fusion, which occur frequently in neuroblastoma, can promote neuroblastoma development." (PMID 36361605, 2022). "We found ATRX mutations in 8/68 samples (11.8%), 6 of which were classified as ALT[+] neuroblastomas, and 2 of which were ambiguous." (PMID 36153564, 2022).
neuroblastoma (continued). "In high-risk neuroblastoma, the commonest somatic variants encountered include ALK, PTPN11, and ATRX." (PMID 35768791, 2022). "As previously reported for neuroblastoma, the mutation frequencies were generally low, with ALK (9%), PTPN11 (3%) and ATRX (3%) mutations being the most common." (PMID 36175618, 2022). "The respective mutation frequencies were similar to that of North American neuroblastoma patient populations that were interrogated with whole exome sequencing (WES) (ALK, 8% versus 9.2%; ATRX, 3% vs 2.5%)." (PMID 35768791, 2022). "In this first focused description of the mutational landscape of neuroblastoma in an Asian population, prevalence of mutations resembled Western series, most commonly involving genes such as ALK and ATRX." (PMID 35768791, 2022). "In contrast, recent high-throughput genome-wide studies have revealed that there were few recurrent somatic alterations in high-risk neuroblastoma, except MYCN ALK ATRX and TERT." (PMID 33465163, 2021). "For example, in each neuroblastoma tumour sample, a mutation was present in only one out of five putative driver genes—ALK, ATRX, PTPN11, MYCN or NRAS." (PMID 34434669, 2021). "TERT rearrangements were detected in 3 out of 20 neuroblastomas, and ATRX alterations were detected in 4 neuroblastomas (2 SNV and 2 losses)." (PMID 34442335, 2021). "ATRX-mutant neuroblastomas were significantly more likely to have ALT than ATRX wild-type tumors (89.5% (17/19) vs. 22.2% (4/18); p < 0.0001, two-tailed Fisher’s exact test)." (PMID 32060267, 2020). "Here we show that ATRX mutations and MYCN amplification are mutually exclusive across all ages and stages in neuroblastoma." (PMID 32060267, 2020). "Next, we induced the expression of MYCN in ATRX-mutant neuroblastoma cells by using a doxycycline-inducible vector." (PMID 32060267, 2020). "Here, we show that amplification of the MYCN oncogene and inactivation of the ATRX tumor-suppressor gene are mutually exclusive in neuroblastomas from patients of all ages and stages of disease." (PMID 32060267, 2020). "Although the inability of ATRX-mutant neuroblastoma cells to resolve G4 structures promotes tumorigenesis by preventing differentiation, it also causes DNA-replicative stress and slows tumor growth." (PMID 32060267, 2020). "Autopsy tumor material from a patient with ATRX-mutant neuroblastoma (SJNBL030014_D) was also included." (PMID 32060267, 2020). "Specifically, the region with MYCN amplification had a high mitosis–karyorrhexis index and was less likely to have ultrabright telomere foci, characteristic of ALT, in ATRX-mutant neuroblastoma cells." (PMID 32060267, 2020). "This is in keeping with a recent publication also showing that ATRX mutations and MYCN amplification are synthetically lethal in neuroblastoma." (PMID 32375866, 2020). "As a result, gene expression is attenuated and ATRX-mutant neuroblastoma cells continue to proliferate." (PMID 32060267, 2020). "The comprehensive genome-wide analysis performed here allowed us to discover age-associated alterations in MYCN, TERT, PTPRD, and Ras pathway alterations, which together with ATRX represent the majority of common driver gene alterations in neuroblastoma." (PMID 33056981, 2020). "Second, ATRX-mutant neuroblastomas have worse outcome, but patients with ATRX/DAXX-mutant PanNETs tumors have prolonged survival." (PMID 32060267, 2020). "Our analysis found significant variation in immune marker expression, including markers of response to checkpoint blockade therapy, and identified ATRX deletions as a potential biomarker of immune infiltrated tumors in MYCN-NA neuroblastoma." (PMID 32275708, 2020).